BRCA1 (BRCA1 DNA repair associated)
Diseases named in the same sentence as BRCA1 in open-access papers (continued):
Sharing a sentence is not in itself a finding about the gene and the disease.
ovarian carcinoma (continued). "The original concept of synthetic lethality between PARP inhibitors and breast and ovarian cancer mutations in BRCA1/2 has now expanded to include a range of cancer types exhibiting homologous recombination deficiency and replication stress." (PMID 32029455, 2020). "Subsequently, in the expansion phase, only ovarian cancer carriers of BRCA1 or BRCA2 mutations were enrolled." (PMID 32481735, 2020). "Germline mutations in BRCA1 are responsible for a large proportion of inherited predispositions to breast and ovarian cancer." (PMID 32053991, 2020). "PARP inhibitor was shown to be effective, especially in ovarian cancer with HRD or BRCA1/2 mutation." (PMID 32813918, 2020). "While monoallelic mutations tend not to cause full FA, they have been linked to increased risk of cancer for several FA proteins, for example germline mutations in BRCA1/2 lead to increased familial breast and ovarian cancer risk." (PMID 36046263, 2020). "PARPis have thus been clinically approved for use in ovarian cancer patients with either germline or somatic BRCA1/2 mutations." (PMID 32483276, 2020). "Testing for BRCA1 and 2 mutations is nowadays used to screen for cancer susceptibility in women with a family history of breast or ovarian cancer." (PMID 32005245, 2020). "In ovarian cancer, where the rate of somatic mutation is higher compared to the other cancers, PARPi have shown efficacy in patients carrying mutations of BRCA1/2, either germline or somatic, but also in wild-type BRCA1/2." (PMID 32605126, 2020). "It is estimated that more than 20% of ovarian cancer cases are associated with a genetic predisposition that is only partially explained by germline mutations in the BRCA1 and BRCA2 genes." (PMID 32359370, 2020). "We found one retrospective cohort study and one case–control study regarding the association of fertility treatments and ovarian cancer risk in BRCA1/2 mutation carriers to include in our review." (PMID 32719921, 2020). "BRCA1 is a well-known breast and ovarian cancer susceptible gene that is frequently mutated in familial breast and ovarian cancers." (PMID 32257107, 2020). "The tumor suppressor breast cancer 1 DNA repair-associated gene (BRCA1) was initially identified as a tumor suppressor of breast and ovarian cancer." (PMID 31963223, 2020). "As a result, rucaparib was approved in 2016 for advanced ovarian cancer with germline and somatic BRCA1/2 mutations." (PMID 32029455, 2020). "It is known that approximately 10–15% of ovarian cancer patients harbor a germline mutation in genes encoding BRCA1 and BRCA2 proteins, which are involved in the process of homologous recombination (HR) that mediates repair of double stranded DNA breaks." (PMID 31898520, 2020). "Despite the lack of such antibody, some studies showed a correlation between BRCA1 mutation status and protein expression for ovarian carcinomas." (PMID 32481735, 2020). "In this study we aimed to identify a prognostic signature in BRCA1/2 mutations to predict disease progression and the efficiency of chemotherapy ovarian cancer (OV), the second most common cause of death from gynecologic cancer in women worldwide." (PMID 32950050, 2020). "Poly(ADP-ribose) polymerase inhibitors (PARPis) specifically target homologous recombination deficiency (HRD) cells and display good therapeutic effect in women with advanced-stage BRCA1/2-mutated breast and epithelial ovarian cancer (EOC)." (PMID 33213473, 2020). "The study indicates that in the Indian population, mutations in the BRCA1/2 genes are the major contributors 37/144 (25.69%) for hereditary breast and/or ovarian cancers." (PMID 33552952, 2020). "For ovarian cancer, cumulative risk at age 80 years was estimated to 44% for BRCA1 carriers and 17% for BRCA2 carriers." (PMID 32025337, 2020).
ovarian carcinoma (continued). "Another gene we found was BRCA1 which is already known to be one of the genes that can cause breast and ovarian cancer when mutated and that is now being linked to other types of cancer such as melanoma." (PMID 33148191, 2020). "This shows that using the LST signature is more efficient for predicting survival of ovarian cancer patients than testing the presence of BRCA1/2 mutations." (PMID 32256521, 2020). "For example, the participants with the BRCA1 variant were in their sixties, which is still relatively young in terms of clinical manifestation of genetic breast or ovarian cancer." (PMID 32272925, 2020). "As far as homologous recombination in epithelial ovarian cancer is concerned, both germline and somatic BRCA1/2 mutations constitute the most common alterations, being detected in roughly 17% and 3% of HGSOCs, respectively." (PMID 32455819, 2020). "For example, breast and ovarian cancers frequently possess mutations of BRCA1 or BRCA2, which are vital genes of homologous recombination (HR), and these cancers often show the mutation signature with a distinctive pattern of substitutions and deletions." (PMID 33299637, 2020). "As expected, LSTHi ovarian cancers were associated with BRCA1/2 mutations, BRCA1 or RAD51C promotor methylation and showed increased sensitivity to platinum-based chemotherapy." (PMID 32256521, 2020). "The breast cancer susceptibility protein 1 (BRCA1) plays a central role in the suppression of human breast and ovarian cancer." (PMID 32583165, 2020). "The aim of this study was to identify a novel lncRNA prognostic biomarker to provide potentially new and accurate biological indicators for the early diagnosis and monitoring of prognosis of ovarian cancer bearing BRCA1/2 mutations." (PMID 32950050, 2020). "PARP is involved in multiple aspects of DNA repair, and the PARP inhibitor olaparib has recently been approved for treating ovarian cancers with BRCA1/2 mutations." (PMID 32778095, 2020). "All these comparisons were evaluated for ovarian cancer etiology, BRCA1 mutation carriage and the ovarian cancer risk." (PMID 32854743, 2020). "Recent clinical trials showed that PARP inhibitors and platinum are effective in treating ovarian cancer patients with mutations of BRCA1, BRCA2, and other genes encoding proteins involved in HR32." (PMID 32457312, 2020). "In high-grade serous ovarian cancer (HGSOC), which comprises the majority of epithelial ovarian cancer cases, germline and somatic mutations in BRCA1/2 are detected in 17–25% of patients, with somatic mutations representing 18–30% of all BRCA1/2 mutations." (PMID 32164585, 2020). "It is interesting to note that various PARP1 inhibitors are in clinical trials; however, they have geared towards BRCA1/2 or DNA damage repair deficiency in breast and ovarian cancers." (PMID 32455851, 2020). "PARP1 mediated ADP ribosylation is a critical step in single-strand D.N.A. damage repair, and its inhibition is synthetically lethal in BRCA1 deficient breast and ovarian cancers." (PMID 32455851, 2020). "One notable example is the PARP inhibitor used in the treatment of inherited breast and ovarian cancer patients with BRCA1 or BRCA2 gene mutations." (PMID 33299637, 2020). "We aimed to find biological markers for early diagnosis of ovarian cancer by investigating BRCA1 gene mutation carrier monozygotic discordant twins and their high risk healthy family individual’s miRNAs." (PMID 32854743, 2020). "In this study, through mutational analysis of both genes from 101tumor tissues, we established the frequency and type of BRCA1/2 mutations in Vietnamese patients with ovarian cancer." (PMID 32856862, 2020). "Genetic mutations in BRCA1, which is crucial for the process of DNA repair and maintenance of genomic integrity, are known to increase markedly the risk of breast and ovarian cancers." (PMID 31467430, 2020).
ovarian carcinoma (continued). "This method can particularly be useful for high-risk women with BRCA1/2 mutations or a family history of breast or ovarian cancers who need more frequent serum biomarkers measurements." (PMID 33322519, 2020). "This included 142 breast and/or ovarian cancer and 7 prostate cancer cases with altogether 84 unique BRCA1/2 variants." (PMID 32486089, 2020). "In this study, we investigated how replication is perturbed in BRCA1-deficient cancer cells treated with multiple doses of cisplatin, a crosslinking agent frequently used to treat ovarian cancers." (PMID 31676232, 2020). "In conclusion, we have characterized the mutation spectrum of BRCA1/BRCA2 in a consecutive series of ovarian carcinomas, observing a frequency of 19.3% of deleterious variants, 13.3% germline, and 5.9% somatic." (PMID 32850417, 2020). "Olaparib has been approved as maintenance therapy following first line treatment for BRCA1/2 mutated ovarian cancers in the EU and USA since 2014." (PMID 36046263, 2020). "For example, BRCA1 mutations are well-known to be frequently linked with the occurrence of human ovarian cancer." (PMID 33109073, 2020). "In 2014, olaparib was approved as maintenance therapy for platinum-sensitive advanced ovarian cancer with germline mutations in DNA repair genes BRCA1/2 that are required for the homologous recombination (HR) pathway of double-strand break (DSB) repair." (PMID 32029455, 2020). "We aim to explore the occurrence of BRCA1/2 mutations in 101 Vietnamese patients with ovarian cancer including serous (n = 58), endometrioid (n = 14), mucinous (n = 24), and clear cell (n = 5) carcinomas." (PMID 32856862, 2020). "Similar to the approach employing a PARP inhibitor targeting BRCA1 mutations in breast and ovarian cancers, several preclinical studies on the inhibition of ATM have been performed to enhance radio-sensitivity in other solid tumors and high-grade gliomas." (PMID 32736562, 2020). "To investigate how to overcome acquired PARPi resistance in BRCA mutant ovarian cancer cells, we used a well-established human high grade serous ovarian cancer cell line containing a frameshift germline BRCA1 mutation (UWB1.289, hereafter referred to as UWB1)." (PMID 32098452, 2020). "BRCA1/2 VUSs represent an important clinical issue in risk assessment for the breast/ovarian cancer families (HBOC) families." (PMID 33159495, 2020). "The total productivity gain of genetic testing for HIV drug resistance was the highest (2,964 million baht), followed by BRCA1/2 gene mutation screening for breast and ovarian cancers (51 million baht)." (PMID 33338033, 2020). "Regarding breast and ovarian cancer (BC and OC), mutations in BRCA1, along with BRCA2 and few other genes, are responsible for only a fraction of familial cases." (PMID 32276467, 2020). "A meta-analysis confirmed significantly reduced risk for ovarian cancer for BRCA1 (SRR = 0.51; 95% CI 0.40–0.65) and BRCA2 mutations carriers (SRR = 0.50; 95% CI 0.29–0.89) associated with use of OC." (PMID 32140806, 2020). "Among those meeting criteria for only Lynch syndrome, 8.8% of PVs occurred in BRCA1/2, 36.1% in other breast and/or ovarian cancer genes, and 8.8% in other cancer predisposition genes." (PMID 31406321, 2020). "Patients with germline BRCA1/2 mutations were diagnosed at a significantly younger age and were more likely to have a family history of breast and/or ovarian cancer." (PMID 33194720, 2020). "This was even more pronounced in platinum-resistant versus platinum-sensitive ovarian cancer, with almost 50% of platinum-resistant cancer (12 out of 26) showing BRCA1/2 reversion mutations." (PMID 32833070, 2020). "Ovarian cancer with BRCA1 or BRCA2 mutations had increased immune infiltrates compared to those without mutations." (PMID 33282564, 2020). "Though breast and ovarian cancer due to BRCA1 mutations have a peak incidence in the fourth decade of life, cumulative incidence of these cancers increases till 80 years of age." (PMID 32272925, 2020).
ovarian carcinoma (continued). "The presence of ovarian cancer or a germline BRCA1 mutation favored a composition of the cervicovaginal microbiota (i.e., a type O community) that is more commonly seen in older than in younger women." (PMID 32133297, 2020). "The miRNA expression profiles were identified to be statistically significant in the evaluation of ovarian cancer etiology, BRCA1 mutation status, and ovarian cancer risk in accordance with the obtained data." (PMID 32854743, 2020). "The data also suggest that BRCA1/2 germline mutation related breast and ovarian cancers express range of phenotypes similar to sporadic cancers and therefore it is unlikely that they represent unique phenotypic identity within TNBC or HGSOC." (PMID 32164626, 2020). "Optimum timing of RRSO should take into account reported age-specific incidences of ovarian cancer among BRCA1 and BRCA2 mutation carriers." (PMID 31948486, 2020). "Women with BRCA1/2 gene mutation are considered as being at a higher risk of developing breast and/or ovarian cancer." (PMID 33575207, 2020). "The potent antitumor effect of PARPi was originally observed in tumors harboring germline BRCA1/2 mutations (gBRCA1/2m), such as familial breast and ovarian cancer." (PMID 32526888, 2020). "The fifth BRCA1 pathogenic variant is c.66_67delAG (p.Glu23fs), it was detected in two patients one with triple negative breast cancer and the second with ovarian cancer." (PMID 32778078, 2020). "Inherited mutations in the BRCA1 gene are behind an increase in the breast and ovarian cancer risk in women." (PMID 32471217, 2020). "Olaparib is FDA approved, for women with advanced ovarian cancer and a BRCA1/2 mutation, after they have completed the first line of platinum-based chemotherapy." (PMID 32867128, 2020). "PARP inhibitors (PARPi) were the first approved cancer drugs that specifically targeted the DNA damage response in BRCA1/2 mutated breast and ovarian cancers." (PMID 33015058, 2020). "Niraparib also increases progression-free survival in patients with wild-type BRCA1/2 ovarian cancers, though less effectively than in patients with BRCA mutations." (PMID 32295316, 2020). "BRCA1 is ubiquitously expressed, and it remains a mystery why BRCA1 mutation leads specifically to breast and ovarian cancer." (PMID 32455662, 2020). "In these studies, the frequency of germline pathogenic variants in BRCA1 in ovarian cancer cases were 5.1%, 3.6%, 3.7%, and 8.6%, respectively, and 3.9%, 3.3%, 4.0%, and 4.5% in BRCA2." (PMID 33086730, 2020). "The cumulative lifetime risk for ovarian cancer is 44% (95% CI 36–53) for BRCA1 and 17% (95% CI 11–25) for BRCA2 mutation carriers." (PMID 32513307, 2020). "Germline mutations in Breast Cancer gene 1 (BRCA1) are associated with familial breast and ovarian cancers." (PMID 32722046, 2020). "This allowed them to investigate its impact on breast and ovarian cancer risk in individuals carrying pathogenic BRCA1 and BRCA2 mutation." (PMID 32255263, 2020). "Ovarian cancer patients with deleterious variants in BRCA1 and BRCA2 are characterized by genomic instability within their tumours." (PMID 33086730, 2020). "As new treatment options are developed to reduce the risk of breast and ovarian cancer in women who carry the BRCA1 or BRCA2 genetic mutation, it will become increasingly important to understand women’s preferences for risk-reducing treatment." (PMID 33014209, 2020). "It has been reported that the average cumulative risks in BRCA1-mutation carriers by age of 70 were 65% and 39% for breast and ovarian cancers respectively and the corresponding estimates for BRCA2 were 45% and 11%." (PMID 33240314, 2020). "And PARP inhibitors are more sensitive to the treatment of ovarian cancer patients with BRCA1/2 mutations." (PMID 33157956, 2020). "BRCA1 (BRCA1 DNA repair associated) is a tumor suppressor gene and related to hereditary breast and ovarian cancer." (PMID 32685473, 2020).
ovarian carcinoma (continued). "After comparison upregulated and downregulated miRNAs related to mutation carriage in BRCA1 gene and epithelial ovarian cancer etiology were determined." (PMID 32854743, 2020). "For ovarian cancer, the cumulative cancer risk to age 80 years is estimated to be 44% (95% CI = 36–53%) and 17% (95% CI = 11–25%) for BRCA1 and BRCA2 pathogenic variant carriers, respectively." (PMID 32772980, 2020). "Association of RAD52 S346X and risk of developing breast or ovarian cancer for BRCA1 and BRCA2 carriers." (PMID 32175645, 2020). "The specific significant factors were older age, having child(ren), being a BRCA1/2 carrier, mastectomy history, perceived risk for ovarian cancer, and perceived advantages of RRSO, whereas objective cancer risk was not significant." (PMID 36312308, 2020). "The BRCA1 c.3331_3334delCAAG founder mutation has been reported in hereditary breast and ovarian cancer families from multiple Hispanic groups." (PMID 33087180, 2020). "As the functions of BRCA1/2 have been studied thoroughly, certain deleterious mutations on BRCA1/2 were verified as predisposing with familial breast and ovarian cancer." (PMID 32879886, 2020). "Pathogenic germline variants in BRIP1 are the most common mutation found in ovarian cancer after BRCA1/2 with a frequency of approximately 1% of the EOC cases." (PMID 33086730, 2020). "These reversion mutations have been identified in patients diagnosed with both germline and somatic BRCA1/2 mutated breast and ovarian carcinomas." (PMID 33015058, 2020). "Compared with wild-type BRCA genotype patients, patients with advanced-stage ovarian cancer and BRCA1/2 mutations have been reported to have higher clinical response rates to platinum-based chemotherapy." (PMID 32131779, 2020). "For BRCA1 mutation carriers, four of the included studies reported a risk reduction of ovarian cancer associated with use of OC." (PMID 32140806, 2020). "Human BRCA1 is a susceptibility gene for breast and ovarian cancers that functions as a tumor suppressor protein responsible for mediating signal transduction in DDR and DNA repair and for destroying cells if repair is unsuccessful." (PMID 32005289, 2020). "The largest study included 1 ovarian cancer case with BRCA1 and 2 mutation, 670 ovarian cancer cases and 2043 controls with BRCA1 mutation as well as 128 cases and 380 controls with BRCA2 mutation." (PMID 32140806, 2020). "Because hRAD52 and BRCA2 play distinct roles in DSB repair, we examined the ability of the RAD52 S346X truncation variant to act as a modifier of susceptibility to breast and ovarian cancers in BRCA1 and BRCA2 mutation carriers." (PMID 32175645, 2020). "SBS3 is observed in breast, pancreatic, and ovarian cancers, and was related to somatic and germline BRCA1/2 mutations as well as defective homologous recombination (HR) base repair." (PMID 32886187, 2020). "To date, several studies have reported the BRCA1/2 pathogenic variants from breast or ovarian cancer in Chinese populations with diverse results." (PMID 32879886, 2020). "Previous studies showed that advanced-stage ovarian cancer patients with BRCA1/2 mutations tend to have higher response rates to platinum-based chemotherapy, longer PFS, and a higher benefit from NAC." (PMID 32131779, 2020). "The cumulative risk of developing ovarian cancer in BRCA1 and BRCA2 carriers ranges from 40 to 59% and 16 to 18%, respectively." (PMID 33036656, 2020). "And even for BRCA1/2-associated ovarian cancer, which is very close to sporadic ovarian cancer in terms of histopathology, the age of onset is at least 10 years earlier (59 years in BRCA1 vs 69 years for sporadic OC)." (PMID 32719921, 2020).